Y_RNA (Y RNA )
Gene: Miscellaneous RNA gene on chromosome 17 (30,344,503 to 30,344,604, reverse strand). Ensembl gene ENSG00000207132.
Homologues: Orthologues: chimpanzee Y_RNA (98% identical), macaque Y_RNA (94% identical). Paralogues in human: Y_RNA (88% identical), RNY3 (87% identical), Y_RNA (87% identical), Y_RNA (86% identical), Y_RNA (85% identical), RNY3P1 (84% identical), RNY3P16 (84% identical), Y_RNA (84% identical), Y_RNA (83% identical), RNY3P9 (82% identical), Y_RNA (82% identical), RNY3P13 (81% identical), and 94 more.